ENSG00000232299 (novel transcript)
Gene: Long non-coding RNA gene on chromosome 6 (112,476,538 to 112,481,636, reverse strand). Ensembl gene ENSG00000232299.
Gene Ontology:
Biological process: RNA processing
Cellular component: nucleolus